XKR8 (XK related 8)
Description:
[XK-related protein 8, processed form]: Phospholipid scramblase that promotes phosphatidylserine exposure on apoptotic cell surface. Phosphatidylserine is a specific marker only present at the surface of apoptotic cells and acts as a specific signal for engulfment. Required for the clearance of apoptotic cells, such as engulfment of apoptotic germ cells by Sertoli cells, clearance of senescent neutrophils or regulation of bipolar cell numbers in the retina (By similarity). In the hippocampus, phosphatidylserine exposure also acts as a specific 'eat-me' marker for axon pruning during brain development (By similarity). Has no effect on calcium-induced exposure of phosphatidylserine. Promotes myoblast differentiation and survival. (Microbial infection) Incorporated into Ebola virus-like particles, where its phospholipid scramblase activity is required to promote phosphatidylserine exposure on the surface of viral particles. Externalization of phosphatidylserine on the surface of viral particles is required for uptake by host cells.
Synonyms: hXkr8; XRG8; FLJ10307
Tractability: Small molecule: a structure with a bound ligand is known. Antibody: UniProt places it where antibodies can reach, with high confidence; its Gene Ontology location is reachable by antibodies, with high confidence; UniProt predicts a signal peptide or a membrane-spanning region.
Gene: Protein-coding gene on chromosome 1 (27,959,588 to 27,968,093, forward strand). Ensembl gene ENSG00000158156.
Subcellular location: Cell membrane; Cytoplasm, perinuclear region
Subcellular location (Human Protein Atlas): Golgi apparatus
Gene Ontology:
Molecular function: phospholipid scramblase activity
Biological process: engulfment of apoptotic cell; phosphatidylserine exposure on apoptotic cell surface; positive regulation of myoblast differentiation; apoptotic process involved in development; neutrophil clearance; synapse pruning
Cellular component: plasma membrane; membrane; perinuclear region of cytoplasm
Genetic constraint (gnomAD): Loss-of-function variants: 10 observed, 11.79 expected, observed/expected ratio (o/e) 0.85, 90% interval 0.52 to 1.43. The upper end of that interval is the gene's LOEUF score, 1.43, which puts it in group 5 of 6, group 1 being the genes least tolerant of losing a copy. Missense variants: 411 observed, 472.56 expected, observed/expected ratio (o/e) 0.87, 90% interval 0.8 to 0.94. Synonymous variants: 213 observed, 224.65 expected, observed/expected ratio (o/e) 0.95, 90% interval 0.85 to 1.06.
Homologues: Orthologues: chimpanzee XKR8 (99% identical), macaque XKR8 (96% identical), dog XKR8 (82% identical), pig XKR8 (79% identical), mouse Xkr8 (69% identical), rat Xkr8 (68% identical), tropical clawed frog xkr8 (41% identical), zebrafish xkr8.3 (37% identical), zebrafish xkr8.2 (32% identical), zebrafish xkr8.1 (29% identical), zebrafish xkr8.4 (28% identical), Drosophila melanogaster CG18635 (17% identical). Paralogues in human: XKR7 (30% identical), XKR4 (30% identical), XKR6 (30% identical), XKR9 (27% identical), XKR5 (22% identical).
Diseases named in the same sentence as XKR8 in open-access papers:
XKR8 is named in the same sentence as 15 diseases in open-access papers, as found by Europe PMC text mining. Sharing a sentence is not in itself a finding about the gene and the disease. The quoted sentences say what the papers report.
autoimmune disease (2 papers, 2019 to 2023). A disorder resulting from loss of function or tissue destruction of an organ or multiple organs, arising from humoral or cellular immune responses of the individual to their own tissue constituents. "Furthermore, impaired XKR8-mediated PtdSer exposure in apoptotic lymphocytes and aged neutrophils activates the immune system, causing lupus-like autoimmune disease in mice." (PMID 37101210, 2023). "Additional support for the immuno-regulatory role of PS exposure is that mice lacking the phospholipid scramblase, XKR8, exhibited reduced clearance of apoptotic lymphocytes and neutrophils, and an SLE-like autoimmune disease." (PMID 31665027, 2019).
breast carcinoma (2 papers, 2025). "For example, surveying the Kaplan meier database suggest that expression levels of Xkr8 or TMEM16F are associated with poorer overall survival in breast cancer (SFig 1)." (PMID 40391322, 2025). "For example, surveying the Kaplan–Meier database suggests that expression levels of Xkr8 or TMEM16F are associated with poorer overall survival in breast cancer." (PMID 41198619, 2025). "Xkr8 knockout on tumor cells reduces tumor growth in vivo in the orthotopic E0771 breast cancer model." (PMID 40391322, 2025). "Here, in an effort to better understand the contributions of apoptotic vs live cell PS-externalization to tumorigenesis and immune evasion, we employed an E0771 orthotopic breast cancer model and genetically ablated Xkr8 and TMEM16F using CRISPR/Cas9." (PMID 40391322, 2025). "Here, in an effort to better understand the contributions of apoptotic vs live cell PS-externalization to tumorigenesis and immune evasion, we employed an EO771 orthotopic breast cancer model and genetically ablated Xkr8 and TMEM16F using CRISPR/Cas9." (PMID 41198619, 2025). "Using an E0771 luminal B orthotopic breast cancer model, we show that E0771 cells preferentially express both Xkr8 and TMEM16F over other isoforms, and that E0771 tumor-bearing transplanted mice externalized PS in the tumor microenvironments as evident by the homing of PS-targeting mAbs." (PMID 40391322, 2025). "Using an EO771 luminal B orthotopic breast cancer model, we show that EO771 cells preferentially express both Xkr8 and TMEM16F over other isoforms, and that EO771 tumor-bearing transplanted mice externalized PS in the tumor microenvironments as evident by the homing of PS-targeting mAbs." (PMID 41198619, 2025).
auditory neuropathy (1 paper, 2023). A hearing disorder characterized by impaired transmission of signals through the auditory nerve, resulting in mild to severe hearing loss and poor speech perception. "We identified a variant in the XKR8 gene that is relevant to auditory neuropathy." (PMID 37101210, 2023). "Transgenic mutant mice exhibited late-onset auditory neuropathy, and their altered XKR8 protein localization in the inner ear confirmed the damaging effects of this variant." (PMID 37101210, 2023).
Cerebral ischemia (1 paper, 2024). Restriction of arterial blood supply to the brain associated with insufficient oxygenation to support the metabolic requirements of the tissue. "While a different scramblase, XKR8, normally facilitates phosphatidylserine exposure as the “eat-me” signal on apoptotic cells, a recent study showed that exposure of phosphatidylserine on dorsal root ganglion neurons after cerebral ischemia is reduced with removal of TMEM16F." (PMID 38941274, 2024).
cognitive decline (1 paper, 2025). "Higher levels of NNT, MYO15A, and GCA were protective in females; greater expression of PEPD, CTNNBL1, MVB12A, XKR8, WBP1L, and GALNT7-DT were associated with faster cognitive decline in females." (PMID 40166028, 2025).
colorectal tumor (1 paper, 2023). "siRNA-mediated downregulation of Xkr8 reportedly leads to colorectal tumor reduction, and the question followed whether modulation of ADAM sheddase activity might play a role in this context." (PMID 37623781, 2023). "siRNA-mediated downregulation of Xkr8 led to diminished PS exposure and reduced release of EREG in a colorectal tumor cell line." (PMID 37623781, 2023).
deafness (1 paper, 2023). An inherited or acquired condition characterized by the complete loss of the ability to hear from one or both ears. "Thus far, studies of XKR8 have focused on cell apoptosis; there are no reports of a relationship between XKR8 and the inner ear or deafness." (PMID 37101210, 2023).
Ebola (1 paper, 2018). "Here, we demonstrate that co-expression of the major matrix protein VP40 and GP promotes trafficking of Xkr8 to budding sites in the PM via GP-positive vesicles and that Xkr8 is incorporated into Ebola VLPs." (PMID 29338048, 2018). "We next examined the role of the incorporated Xkr8 in the externalization of PS on the surface of Ebola VLPs." (PMID 29338048, 2018).
Infertility (1 paper, 2023). "Apoptotic stimuli do not induce PtdSer exposure in XKR8-null germ cells, which leads to infertility in male mice." (PMID 37101210, 2023).
pancreatic cancer (1 paper, 2023). "In line with the present results in Caco-2 cells, co-delivery of Xkr8 siRNA and a chemotherapeutic agent led to drastic inhibition of tumor growth in colon and pancreatic cancer models." (PMID 37623781, 2023).
cancer (5 papers, 2020 to 2025). A tumor composed of atypical neoplastic, often pleomorphic cells that invade other tissues. "Conversely, siRNA-mediated downregulation of Xkr8 in colorectal Caco-2 cancer cells led to decreased PS externalization upon induction of apoptosis, which was accompanied by reduced shedding of endogenously expressed EREG and reduced cell survival." (PMID 37623781, 2023). "Moreover, Xkr8 inactivation in combination with the anti-PD-1 regimen resulted in the complete elimination of cancers in mice." (PMID 37664062, 2023). "The research team also established PSin models when cancer cells lacked the PS-disrupting enzyme Xkr8 in vivo and cannot expose PS during normal apoptosis." (PMID 37664062, 2023). "However, there are no any reports or laboratory data on the relationship between cancer and the following genes: GSG1L, CRB1, XKR8, ZNF680, ZNF284, and ZNF780B, which is part of the 17-gene signature." (PMID 32596394, 2020). "The other six genes (GSG1 like (GSG1L), crumbs cell polarity complex component 1 (CRB1), XK-related 8 (XKR8), zinc finger protein 680 (ZNF680), zinc finger protein 284 (ZNF284), and zinc finger protein 780B (ZNF780B)) are not mentioned in the cancer research area until now." (PMID 32596394, 2020).
tumor (5 papers, 2018 to 2025). "For example, Xkr8 deficient tumor cells showed enhanced secretion of cyclic GAMP to activate STING on neighboring cells." (PMID 40391322, 2025). "While our present studies are consistent with the idea of cell-intrinsic mediated events on the dying and viable tumor cells, via the cell-intrinsic loss of either Xkr8 or TMEM16F, it is still unclear what other cell types may contribute to PS externalization in the complex tumor microenvironment." (PMID 40391322, 2025). "Moreover, using single cell RNAseq, these authors showed increased infiltration of CD8+ cytotoxic T cells and reduced exhausted T cells suggesting that the loss of Xkr8 promoted a type of immunogenic death response perhaps involving the cross-presentation of tumor antigens by APCs." (PMID 40391322, 2025). "TMEM16F KO apoptotic cells were efficiently engulfed by BMDMs, suggesting distinct functions for scramblases, showing that Xkr8 mediated PS externalization on apoptotic tumor cells is essential for recognition by BMDMs." (PMID 40391322, 2025). "Based on the results of the Xkr8 knockdowns that improve host tumor immunity, development of selective inhibitors of Xkr8, or characterization of relevant Xkr8 kinases, warrant further investigation." (PMID 40069722, 2025). "Taken together, while both scramblases affected tumor growth in immunocompetent mice, the mechanisms by which Xkr8 and TMEM16F impinge on immune evasion are likely distinct." (PMID 40391322, 2025). "Together, these observations suggest an active role of an immune component in the tumor regression in Xkr8 KO tumors." (PMID 40391322, 2025). "Complementary gene-silencing experiments were conducted with Caco-2 tumor cells that express high constitutive levels of Xkr8 and ADAM17 substrates." (PMID 37623781, 2023). "When EO771 WT cells or EO771 Xkr8 KO cells were injected into mammary gland fat pads of C57BL6 WT mice for longitudinal tumor volume studies, the Xkr8 KO tumors exhibited significant reduction in tumor growth compared to WT tumors, as evident by tumor volume, tumor weight and spleen weight." (PMID 40391322, 2025). "Silencing Xkr8 has been reported to provide anti-tumor effects in mice." (PMID 37623781, 2023). "To investigate the tumor cell-intrinsic role of PS on tumor cells, we explored targeting PS scramblases TMEM16F and Xkr8 specifically on EO771 tumor cells by CRISPR/Cas9 gene editing." (PMID 41198619, 2025). "Our results provide evidence that both Xkr8 and TMEM16F knockout tumor cells suppress in vivo tumor growth in immunocompetent mice but in NOD/SCID or RAG1 immunoincompetent mice." (PMID 40391322, 2025). "To investigate the cell intrinsic role of PS on tumor cells, we explored targeting PS scramblases TMEM16F and Xkr8 specifically on E0771 tumor cells by CRISPR/Cas9 gene editing." (PMID 40391322, 2025). "Our results provide evidence that both Xkr8 and TMEM16F knockout tumor cells suppress in vivo tumor growth in immunocompetent mice but not in NOD/SCID or Rag1 KO immuno-incompetent mice." (PMID 41198619, 2025). "These genes are paralogs of XKR8 and ANO6/TMEM16F, which mediate an externalization of phosphatidyl serine, creating an immunosuppressive tumor micro environment." (PMID 30429477, 2018). "In our studies, the Xkr8 was only deleted on the tumor cells, not other cells in the tumor microenvironment, nor did we use external chemotherapeutics to enhance tumor cell death in the in vivo studies." (PMID 41198619, 2025). "Ablation of Xkr8 on E0771 tumor cells blocks PS externalization on dying cells without altering cell intrinsic oncogenic properties." (PMID 40391322, 2025). "Another emerging area of PS biology that deserves further attention is whether tumor cells up-regulate or alter expression of Xkr8 or TMEM16F as a cell intrinsic or driver event in host immune evasion and tumor progression." (PMID 40391322, 2025).
tumor (continued). "At the molecular level, PS-out tumor cells engage inhibitory PS receptors including TIM-3, supporting the notion that PS viable cells can contribute to the strong immune-inhibitory responses analogous to Xkr8." (PMID 40069722, 2025). "Similar observations were noted in the Rag1 KO mice, which do not have matured T and B cells, whereby the Xkr8 KO tumors grew similarly as WT evident by both tumor volume and tumor weight." (PMID 40391322, 2025). "When WT EO771 or Xkr8 KO cells were injected into NSG mice, which have a dysfunctional adaptive immune system, the KO tumors grew at a similar rate compared to the EO771 WT tumors, as shown by relative tumor volume, compared to WT at endpoint and tumor weight." (PMID 41198619, 2025). "In the studies reported here, the Xkr8 was only deleted on the tumor cells, not other cells in the tumor microenvironment, nor did we use external chemotherapeutics to enhance tumor cell death in the in vivo studies." (PMID 40391322, 2025). "Another emerging area of PS biology that deserves further attention is whether tumor cells upregulate or alter the expression of Xkr8 or TMEM16F as a cell-intrinsic or driver event in host immune evasion and tumor progression." (PMID 41198619, 2025). "When WT E0771 or Xkr8 KO cells were injected into NSG mice, which have a dysfunctional adaptive immune system, the KO tumors grew at a similar rate compared to the EO771 WT tumors, as shown by tumor volume and tumor weight." (PMID 40391322, 2025). "Subsequently, using CRISPR/Cas9 gene editing to individually knockout Xkr8 or TMEM16F, we show that both PS scramblases directly contribute to immune regulation and tumor growth in immune-competent mice but not in NOD/SCID or Rag1 KO immune-deficient mice." (PMID 41198619, 2025). "Subsequently, using CRISPR/Cas9 gene editing to individually knockout Xkr8 or TMEM16F and, we show that both PS scramblases directly contribute to immune regulation and tumor growth in immune-competent mice but not NOD/SCID or RAG immune-deficient mice." (PMID 40391322, 2025). "While neither the knockout of Xkr8 nor TMEM16F showed defects in cell intrinsic properties related to proliferation, tumor-sphere formation, and growth factor signaling, both knockouts suppressed tumorigenicity in immune-competent mice, but not in NOD/SCID or RAG-knockout immune-deficient strains." (PMID 41198619, 2025). "While neither the knockout of Xkr8 nor TMEM16F showed defects in cell intrinsic properties related to proliferation, tumor-sphere formation, and growth factor signaling, both knockouts suppressed tumorigenicity in immune-competent mice, but not in NOD/SCID or RAG-KO immune-deficient strains." (PMID 40391322, 2025).
XKR8 also shares sentences with these, for which no sentence is quoted: brain glioma (1 paper); glioma (1); lupus (1).